SLC22A13 (solute carrier family 22 member 13)
Description:
Anion antiporter that mediates the transport of urate, orotate and nicotinate in exchange for organic or inorganic anions. Translocates urate and orotate across the apical membrane of proximal tubule epithelial cells and involved in urate renal reabsorption. Possibly involved in orotate renal reabsorption and nicotinate intestinal reabsorption. Mediates urate uptake by an exchange with organic anions such as (S)-lactate, succinate, glutathione and nicotinate. Urate and orotate transports are Cl(-)-dependent. Shows similar transport characteristics as the urate/orotate renal antiporter SLC22A12/URAT1 and may act as a compensator of SLC22A12/URAT1 in certain conditions (Probable).
Synonyms: OAT10; ORCTL-3; ORCTL3; OCTL1; OCTL3
Tractability: Small molecule: it belongs to a druggable protein family. Antibody: UniProt places it where antibodies can reach, with high confidence; its Gene Ontology location is reachable by antibodies, with high confidence; UniProt predicts a signal peptide or a membrane-spanning region. PROTAC: ubiquitination databases record sites on it.
Gene: Protein-coding gene on chromosome 3 (38,265,812 to 38,278,757, forward strand). Ensembl gene ENSG00000172940.
Subcellular location: Apical cell membrane
Pathways (Reactome):
Metabolism: Nicotinate metabolism
Gene Ontology:
Molecular function: nicotinate transmembrane transporter activity; urate transmembrane transporter activity; transmembrane transporter activity
Biological process: negative regulation of fatty acid metabolic process; nicotinate transport; positive regulation of T cell mediated cytotoxicity directed against tumor cell target; urate transport; NAD+ biosynthetic process via the salvage pathway; transmembrane transport
Cellular component: apical plasma membrane; endoplasmic reticulum; extracellular exosome; Golgi apparatus; plasma membrane; membrane
Genetic constraint (gnomAD): Loss-of-function variants: 40 observed, 50.39 expected, observed/expected ratio (o/e) 0.79, 90% interval 0.62 to 1.03. The upper end of that interval is the gene's LOEUF score, 1.03, which puts it in group 4 of 6, group 1 being the genes least tolerant of losing a copy. Missense variants: 690 observed, 734.76 expected, observed/expected ratio (o/e) 0.94, 90% interval 0.88 to 1. Synonymous variants: 282 observed, 302.58 expected, observed/expected ratio (o/e) 0.93, 90% interval 0.85 to 1.03.
Homologues: Orthologues: chimpanzee SLC22A13 (99% identical), macaque SLC22A13 (95% identical), dog SLC22A13 (81% identical), pig SLC22A13 (78% identical), mouse Slc22a13 (73% identical), mouse Slc22a13b (73% identical), rat LOC120094289 (73% identical), rat Slc22a13l1 (70% identical), tropical clawed frog slc22a13 (47% identical), zebrafish slc22a13b (45% identical), Drosophila melanogaster Orct (32% identical), Drosophila melanogaster Orct2 (32% identical), and 38 more. Paralogues in human: SLC22A6 (34% identical), SLC22A14 (34% identical), SLC22A7 (33% identical), SLC22A5 (32% identical), SLC22A8 (32% identical), SLC22A12 (32% identical), SLC22A1 (31% identical), SLC22A11 (30% identical), SLC22A2 (30% identical), SLC22A24 (30% identical), SLC22A4 (29% identical), SLC22A10 (29% identical), and 10 more.
Diseases named in the same sentence as SLC22A13 in open-access papers:
SLC22A13 is named in the same sentence as 13 diseases in open-access papers, as found by Europe PMC text mining. Sharing a sentence is not in itself a finding about the gene and the disease. The quoted sentences say what the papers report.
gout (10 papers, 2020 to 2024). A condition characterized by painful swelling of the joints, which is caused by deposition of urate crystals. "Meta-analysis displayed that rs117371763 (R377C) variant of SLC22A13 gene has significant anti-gout effect." (PMID 35922835, 2022). "As expected, many transporter genes such as URAT1/SLC22A12, GLUT9/SLC2A9, ABCG2/BCRP, NPT1/SLC17A1, and OAT10/SLC22A13 were identified as having an association with gout and SU in addition to several enzyme genes, including the ALDH2 gene, which has a pivotal role in alcohol metabolism." (PMID 38137389, 2023). "This study examines six rare nonsynonymous variants in the SLC22A11, SLC22A13, and SLC17A1 genes found in a cohort of 150 Czech patients of Caucasian origin with primary hyperuricemia and gout." (PMID 38222853, 2024). "A dysfunctional missense variant rs117371763 (p.R377C) of OAT10/SLC22A13, which encodes urate absorber, has also been shown to decrease both gout risk and SU levels by increasing FEUA." (PMID 38137389, 2023). "Dysfunctional missense variant of organic anion transporter 10 (OAT10/SLC22A13), rs117371763 (c.1129C>T; p.R377C), is associated with a lower susceptibility to gout." (PMID 35462902, 2022). "Recent studies have also shown that dysfunctional missense mutation of SLC22A13 gene reduced SUA levels and the risk of gout." (PMID 35922835, 2022). "To date, there are no known variants of the SLC22A13 gene associated with the risk of gout; on the other hand, the polymorphism rs117371763 (p.R377C) is associated with a reduction of gout risk." (PMID 38222853, 2024). "The genetics of hyperuricemia, which is universally accepted to be the cause of gout, involves genes such as SLC2A9 (encodes for GLUT9), SLC22A12 (encodes for URAT1), SLC22A13 (encodes for OAT4) and ABCG2; these are mostly involved in uric acid reabsorption and secretion." (PMID 35456363, 2022). "Furthermore, some association analyses have also shown associations between gout and urate transporter genes URAT1, NPT1, OAT4/SLC22A11 and OAT10/SLC22A13, and scaffold protein genes PDZK1 and LRRC16A, which bind to various transporters and form transportosomes with them." (PMID 31975031, 2020). "In a cohort of 150 Czech patients with primary hyperuricemia and gout, we examined all coding regions and exon–intron boundaries of SLC22A11, SLC22A13, and SLC17A1 using PCR amplification and Sanger sequencing." (PMID 38222853, 2024). "It is certain that SLC22A13, like SLC22A12, can provide effective targets for the treatment of gout." (PMID 35922835, 2022).
kidney cancer (1 paper, 2020). Primary or metastatic malignant neoplasm involving the kidney. "In kidney cancer, SLC22A6, SLC22A7, SLC22A13, SLC25A4, SLC34A1, and SLC44A4 were significantly downregulated." (PMID 32461965, 2020).
kidney tumors (1 paper, 2022). "Before discussing the SLC22 genes identified in this study in relation to renal cell cancer and various oncologic variables (TNM class) used to determine pathologic stage, we note previous work has shown that SLC22A2, SLC22A12, and SLC22A13 are downregulated in human kidney tumors." (PMID 36230695, 2022).
tumor (3 papers, 2022 to 2023). "Five of those are found in comparisons of both tumor types: SLC22A6/OAT1, SLC22A7/OAT2, SLC22A8/OAT3, SLC22A12/URAT1, SLC22A13/ORCTL3." (PMID 36230695, 2022).
cancer (2 papers, 2020 to 2025). A tumor composed of atypical neoplastic, often pleomorphic cells that invade other tissues. "The expression levels of SLC22A6, SLC22A13, SLC25A4, SLC34A1, and SLC44A4 were significantly correlated with the clinical stage of the cancer." (PMID 32461965, 2020). "We used the Oncomine database to analyze the expression levels of SLC22A6, SLC22A7, SLC22A13, SLC25A4, SLC34A1, and SLC44A4 in various cancers and their normal tissues." (PMID 32461965, 2020). "Among the various cancers examined, SLC22A6, SLC22A7, SLC22A13, SLC25A4, and SLC34A1 were significantly downregulated, while SLC44A4 showed different expression patterns in different cancers (upregulated or downregulated)." (PMID 32461965, 2020).
SLC22A13 also shares sentences with these, for which no sentence is quoted: hyperuricemia (4 papers); Acidosis (1); diabetes (1); Hyperinsulinemia (1); Insulin resistance (1); lung carcinoma (1); renal cell cancer (1); renal hypouricemia (1).